BMAL1 (basic helix-loop-helix ARNT like 1)
Diseases named in the same sentence as BMAL1 in open-access papers (continued):
Sharing a sentence is not in itself a finding about the gene and the disease.
tumor (continued). "Importantly, we demonstrate that the expression of the clock gene aryl hydrocarbon receptor nuclear translocator-like protein 1 (BMAL1) positively correlates with patient overall survival and with the expression of T-cell activity and exhaustion markers in the tumor bulk." (PMID 29946530, 2018). "Overall, our data corroborate previous reports regarding the impact of BMAL1 expression on the cellular DNA-repair capacity and indicate that alterations in the tumor-autonomous molecular clock could influence the cellular composition of the surrounding microenvironment." (PMID 29946530, 2018). "Moreover, BMAL1, another core clock transcription factor, was identified to heterodimerize with NPAS2 to bind to the E-box element in the promoter of CDC25A and be associated with the NPAS2-mediated tumor cell survival in HCC." (PMID 28333141, 2017). "Stimulated overexpression of Bmal1 may inhibit tumour growth." (PMID 26019503, 2014). "In CRC, among the core circadian components, BMAL1, ROR, and PER members have been described as tumour suppressors, while CLOCK, NR1D, and CRY members have been described as tumour promoters." (PMID 40564218, 2025). "Enhanced expression of Per2 or Per3 inhibits tumor stem cell proliferation by suppressing Wnt signaling, while reduced PER3 levels stimulate Bmal1 expression and activate Wnt signaling." (PMID 40821111, 2025). "Melatonin’s canonical clock-gene targets (BMAL1, PER2) intersect with T-cell metabolic checkpoints, restoring rhythmic oxidative phosphorylation and IL-2 responsiveness in tumour-infiltrating CD8+ cells." (PMID 40791587, 2025). "Mechanistically, melatonin upregulates the core clock protein BMAL1, which transcriptionally represses its downstream target ALDH3A1, thereby effectively blocking the glycolytic program in tumor cells and suppressing cancer progression." (PMID 41228459, 2025). "The deacetylation of BMAL1 by lactate/interleukin-1 beta (IL-1β) amplifies LDHA expression and tumor growth." (PMID 40725147, 2025). "BMAL1-HIF2α is more sensitive than ARNT-HIF2α is to suppression by PT2399, and the effectiveness of PT2399 for suppressing xenograft tumor growth in vivo depends on the time of day at which it is delivered." (PMID 40595592, 2025). "Given the pleiotropic effects of Bmal1 alterations on tumorigenesis, we speculate that the diverse effects of Bmal1 on tumorigenesis depends on the initial neoplastic cell state and whether Bmal1 modulates tumor initiation versus progression in specific models." (PMID 38245503, 2024). "Taken together, our results suggested a negative feedback loop between KIT and ZSWIM4 in GISTs, where ZSWIM4 serves as a tumor suppressor in GISTs by inhibiting KIT signaling and BMAL1, a key component of the circadian clock pathway." (PMID 38951864, 2024). "NPAS2, with BMAL1, regulates the MYC promoter, influencing cell cycle dynamics and potentially affecting tumour growth." (PMID 39566400, 2024). "Taken together, our findings indicate that ectopic expression of Bmal1 proteins in the YUMM2.1 native state confers immune resistance and altered tumor growth." (PMID 38245503, 2024). "This study emphasizes that targeting BMAL1 can enhance sensitivity of AML cells to ferroptosis inducer RSL3, as well as the tumor treatment drugs venetoclax, dasatinib, and sorafenib." (PMID 38703241, 2024). "In order to study the in vivo mechanism by which BMAL1 regulates ferroptosis through HMGB1, we utilized subcutaneous tumor implantation to establish AML tumor models." (PMID 38703241, 2024). "Bmal1 depletion in mice promotes an anti-inflammatory state, disrupts CD4+ and CD8+ T cell distribution in lymph nodes, and increases tumour growth by reducing CD8+ T cells in tumours." (PMID 39566400, 2024). "Together, these results show that tumor‐ and plasma‐derived latent TGF‐β was converted into active TGF‐β by increased plasmin activity in Bmal1−/− mice." (PMID 37330661, 2023).
tumor (continued). "Numerous studies have shown that circadian rhythm regulators, such as PER2, CLOCK, BMAL1, CRY1, and CRY2, act as tumor suppressors in the liver, ovaries, colon, and lung." (PMID 37524704, 2023). "Analysis conducted on GSE39582, GSE21510 and Cancer Genome Atlas (TCGA) pan-cancer datasets revealed notable down-regulation of BMAL1 expression in BRCA and CRC tumor samples when compared to normal tissues." (PMID 38189049, 2023). "On the other hand, in some cancers, BMAL1 or CLOCK act as oncogenes, but in other cancers and model systems, their targeting is tumor suppressive." (PMID 36895015, 2023). "Consistent with tumor suppression, pharmacological inhibition of TGF‐βR1 abrogated Bmal1‐deletion–triggered tumor fibrosis that showed reduced positive structures of FAP, α‐SMA, DESMIN, PDGFRα, and PDGFRβ." (PMID 37330661, 2023). "Considering that epithelial-mesenchymal transition (EMT) is a mechanism pivotal to tumor metastasis, we investigated the involvement of EMT in BMAL1-regulated HCC metastasis." (PMID 36439870, 2022). "The expression of BMAL1, CLOCK, Rev-Erbα, and PER2 in intraperitoneal macrophages regulated the expression levels of F4/80 and CD11c in tumor tissues." (PMID 35116071, 2022). "Breast cancer cells have dropped the expression of Bmal1, via MT1-RORa1, which is described as acting as a tumor suppressor by inducing the downregulation of Sirt1." (PMID 33535472, 2021). "Overexpression of RORα significantly blocked tumor growth (p = 0.013), and DOX-induced tumors also showed higher BMAL1 protein levels." (PMID 34183658, 2021). "In fact, the role of BMAL1 in CRC development remains poorly understood, in particular its link to EMT, a key process in tumor progression." (PMID 34065633, 2021). "The results showed that the BMAL1 staining area and intensity in tumor tissue were reduced in the GL261 + BV2 (M2) Exosomes group, and by statistical analysis, the expression of BMAL1 protein in this group was reduced (P < 0.05, P < 0.001)." (PMID 33528793, 2021). "When GFP-tagged BMAL1 was consistently overexpressed, tumor migration was significantly alleviated, and increased migration by acidosis was also alleviated in GFP-BMAL1 stable MDA-MB-231 cell lines." (PMID 32316196, 2020). "The current article highlights the role of the mitochondrial melatonergic pathway in GBM/GSC pathophysiology and tumour microenvironment interactions, including via the regulation of the circadian genes CLOCK and Bmal1, which modulate temozolomide efficacy." (PMID 35582450, 2020). "On the other hand, and similar to BMAL1 KD, the downregulation of NR1D1 led to a significant reduction of proliferation (~50% reduction, p = 0.0008) and tumour size (~24% reduction, p = 0.0012)." (PMID 32244760, 2020). "The downregulation of BMAL1 led to significantly lower apoptosis rates for both SW480 and SW620 cells, which is in line with the assumption of the clock acting as a tumor suppressor." (PMID 32295075, 2020). "Altogether, our results suggest an essential role for BMAL1 and NR1D1 in survival of HCT116 tumours and point to an NR1D1 specific role in metastatic potential in vivo." (PMID 32244760, 2020). "The level of BMAL1 was decreased notably in TSCC and as well as in the adjacent non-tumor tissue compared with normal tongue epithelial tissue." (PMID 31151182, 2019). "As anticipated, miR-135b overexpression promoted the growth of subcutaneous xenografts generated by MIA PaCa-2 cells, whereas BMAL1 reintroduction sensitised the cell response to GEM therapy and substantially reduced the sizes and weights of tumours." (PMID 29396463, 2018). "Here, we showed that overexpressing miR-135b significantly facilitated GEM resistance in PC cells, whereas BMAL1 upregulation restored GEM-induced apoptosis and sensitised the pancreatic xenograft tumours to GEM treatment." (PMID 29396463, 2018).
tumor (continued). "In this study, we demonstrate for the first time that CLOCK and BMAL1 promote cytoskeletal F-actin filament formation by regulating the RHOA-ROCK-CFL pathway, revealing a novel mechanism of circadian genes in tumor cells." (PMID 30287810, 2018). "This cluster revealed a lower expression or minor changes in the expression of BMAL1, CLOCK, tumour marker genes, cytokeratins and casein kinases." (PMID 27465361, 2016). "Evidence suggests that disruptions in core circadian clock genes, such as BMAL1 and PER, along with the dysregulation of cellular metabolic pathways, immune responses, and endocrine functions, synergistically facilitate tumor growth and metastasis during nocturnal periods." (PMID 41869447, 2026). "Circadian metabolic rhythmicity offers new insights into tumor heterogeneity, with the core clock components (Clock Circadian Regulator (CLOCK), brain and muscle ARNT-like 1 (BMAL1/ARNTL), Period Circadian Regulator (PER)) acting as master regulators of oncogenic metabolism." (PMID 40725147, 2025). "Independent of specific cancer types, the core clock gene Bmal1 governs the cell proliferation rhythm essential for tumor angiogenesis by regulating the cell cycle genes CCNA1/CDK1." (PMID 41143275, 2025). "In order to explore the influence of BMAL1 in vivo on the responsiveness of AML cells to venetoclax, dasatinib, and sorafenib, we conducted AML tumor modeling by subcutaneously injecting mice with either stable BMAL1-knockout cells or cells transfected with an empty vector." (PMID 38703241, 2024). "Finally, BMAL1 SNPs (rs7396943, rs7938307, rs2279287) were correlated with poorer PFS and OS, and high BMAL1 expression in tumor cells was correlated with unfavorable clinical outcomes in bevacizumab-treated CRC patients." (PMID 38611042, 2024). "BMAL1 drives the transcription of VEGFA conferring resistance to bevacizumab treatment, therefore combining bevacizumab with a CRY2 stabilizer (SHP1705) to inhibit BMAL1 activity led to a decreased tumor volume and an improved OS in mouse models." (PMID 39199569, 2024). "However, higher evidence for an oncogenic function was found for BMAL1 and CLOCK and higher evidence for a tumour suppressor function was found for PER2 and PER3, consistent with their role in the positive respectively negative arm of the clock network." (PMID 38378853, 2024). "Thus, we co-injected BMDMs from WT or BMAL1 KO mice along with KCKO cells into WT mice, and tumor growth was measured." (PMID 39415049, 2024). "Part of the reason is that mutations in BMAL1 and CLOCK are not commonly observed in cancer, implying that they themselves do not commonly function as mutated drivers of tumor initiation." (PMID 37601651, 2023). "By contrast, inhibition of transforming growth factor‐beta receptor 1 (TGF‐βR1) in Bmal1−/− mice produced a markedly inhibitory effect on tumor growth, which was indistinguishable from the vehicle‐treated control tumors grown in Bmal1+/+ mice." (PMID 37330661, 2023). "In vehicle‐treated and SB‐431542 treated Bmal1+/+CRC tumor–bearing mice, there was no elevated expression of p‐Smad2." (PMID 37330661, 2023). "Immunohistochemical analysis reveals that low Bmal1 expression in tumor tissues significantly impact tumor progression and prognosis compared to adjacent non-tumor tissues." (PMID 38189049, 2023). "In this study, we uncovered a non-canonical function of BMAL1 in DSBs repair and tumor chemoresistance." (PMID 36725890, 2023). "Because the Bmal1 gene was deleted in cancer host, but not in cancer cells per se, we next isolated Bmal1−/− tumor stromal cells by fluorescence‐activated single cell sorting (FACS) to explore the key molecular signaling in the stromal components." (PMID 37330661, 2023). "Similarly, a negative relationship between the protein expression levels of BMAL1 and GPAM was observed in 217 HCC tissues and 36-unpaired primary and metastasis tumor tissues from HCC patients." (PMID 36439870, 2022).
tumor (continued). "Given the circadian dysregulation in tumor cells, we investigated circadian rhythms in MDA-MB-231 and MDA-MB-468 cells by monitoring real-time bioluminescence from the introduced stable expression of the Bmal1::Luciferase and Per2::Luciferase (respectively)." (PMID 35440077, 2022). "In this context, pharmacologically restoring BMAL1 expression led to suppression of N-MYC-driven lipogenesis and diminished tumor growth, suggesting that N-MYC and CLOCK-BMAL1 may drive opposing metabolic programs in these cancer cells." (PMID 34299381, 2021). "Both SR1078 and genetic overexpression of RORα effectively restore BMAL1 expression and oscillation, and block tumor growth in MNA, but not in non-MNA orthotopic xenografts, suggesting that the anti-tumor effect of SR1078 is MYCN-dependent." (PMID 34183658, 2021). "CLOCK might interact with HIF-1α/ Bmal1 and activate VEGF to stimulate tumor angiogenesis and metastasis." (PMID 32437452, 2020). "Taken together, these studies support the emerging idea that BMAL1 and CLOCK have tumor promoting qualities in HGGs, while PER (and possibly CRY) may have tumor suppressing roles, though this is likely to be context and cancer dependent." (PMID 32631383, 2020). "Decreased expression of PER1 and PER3 in tumor tissue as such indicate poorer survival rate, decreased PER1 and high BMAL1 expression correlate with poorer outcome and liver metastasis, and high PER2 expression correlate with significantly better disease outcome." (PMID 31379749, 2019). "Crem has been previously implicated as a key player in tumor regulation/suppression 62,63, hence its altered expression also indicates that CJL can increase cancer risk if Bmal1 is nonfunctional while the non-functionality of Cry1/2 has an opposite effect." (PMID 31523185, 2019). "After obtaining BMAL1 knockouts by targeting the gene at two different sites from non-tumorigenic MCF10A and invasive tumorigenic MDA-MB-231 cells, we analysed apoptosis and invasion properties of the cell lines as representative events in tumor development." (PMID 30375470, 2018). "Mice lacking Per1 and 2, Cry1 and 2, or one copy of Bmal1, all show increased spontaneous and radiation-induced tumor development." (PMID 20539819, 2010). "At this time of day, tumor WEE-1 and nuclear BMAL1 levels are higher." (PMID 19688113, 2009). "Circadian genes like PER1 and BMAL1, involved in DNA damage response, may exhibit altered expression in SCLC, potentially affecting the tumor’s response to therapeutic interventions such as radiation and chemotherapy, both of which interact with the circadian control of cell cycle and apoptosis." (PMID 39812541, 2025). "Based on our observation that BMAL1-HIF2α heterodimers are more sensitive to suppression by the HIF2α antagonist PT2399 than ARNT-HIF2α heterodimers are, we predicted that suppression of tumor growth by PT2399 would be greater at the time of day when BMAL1 is more active." (PMID 40595592, 2025). "Increased BMAL1 in ccRCC compared to non-tumor biopsies remains statistically significant when only adjacent samples from the same patients are included in the analysis, suggesting that elevated BMAL1 in ccRCC samples is not an artifact of tissue collection time or differential sample processing." (PMID 40595592, 2025). "Additional findings suggest that the master regulators CLOCK and BMAL1 possess anti-apoptotic functions that contribute to the proliferation of liver cancer cells, while their inhibition leads to dysregulation of WEE1 and p21, ultimately promoting tumor cell death." (PMID 40700255, 2025).
tumor (continued). "Dysregulation of circadian rhythm genes—such as CLOCK, BMAL1, PER, and CRY—may result in abnormal proliferation, metabolic reprogramming, genomic instability, immune evasion, and microenvironmental remodeling in HCC cells, thereby promoting tumor progression." (PMID 41298718, 2025). "Moreover, when reaching the endpoint of the observation, the tumor weight in mice subjected to BMAL1 knockdown was notably reduced compared to the tumor weight in mice without BMAL1 knockdown." (PMID 38703241, 2024). "Increased BMAL1 in ccRCC compared to non-tumor biopsies remains statistically significant when only adjacent samples from the same patients are included in the analysis, suggesting that elevated BMAL1 in ccRCC samples is not an artefact of tissue collection time or differential sample processing." (PMID 39070610, 2024). "Furthermore, the clock gene BMAL1 is higher in ccRCC than in healthy kidneys, unlike in other tumor types." (PMID 39070610, 2024). "However, univariate Cox regression model revealed that BMAL1 expression was not related to T stage, lymphatic invasion, tumor size or tumor location." (PMID 36806631, 2023). "Interestingly, our primary tumor growth results were similar to results by Jiang and colleagues, who used implanted human PDAC cells (BxPC-3 and PANC-1) into immunocompromised mice after shRNA knockdown of Bmal1." (PMID 37262074, 2023). "The percentage of animals with pulmonary metastases in TGF‐βR1 inhibitor‐treated tumor‐bearing in Bmal1−/− mice was identical to those in tumor‐bearing Bmal1+/+ mice, consistent with TGF‐β signaling being responsible for the increased metastasis in CRC tumor–bearing Bmal1−/− mice." (PMID 37330661, 2023). "Treatment of CRC tumors with SB‐431542 in Bmal1+/+ mice did not affect tumor growth." (PMID 37330661, 2023). "However, depletion of BMAL1 promotes cell growth and almost completely rescues the block in cell viability and the apoptosis induced both by SR1078 and RORα overexpression, suggesting that the anti-tumor activity of RORα is dependent on BMAL1." (PMID 34183658, 2021). "In addition, BMAL1 expression did not display significant relationships with age, gender, or tumor size." (PMID 34815366, 2021). "However, our previous study indicated that the expression of CLOCK and BMAL1 demonstrate no circadian rhythmicity in tumor cells." (PMID 30287810, 2018). "However, the ANOVA analysis showed an effect of time, and immunohistochemistry on s.c. tumor slices revealed a significant rhythm of BMAL1 protein levels in DEX-treated tumors, but not in PBS-treated tumors." (PMID 28196531, 2017). "Moreover, arrhythmic Bmal1−/− and Clock∆19 mutants also do not show higher tumor frequencies, although they develop symptoms of accelerating aging under normal conditions (Bmal1−/−), or when subjected to γ-radiation (Clock∆19)." (PMID 28425940, 2017). "However, we did not observe consistent BMAL1-Luc rhythms in TNBC tumor organoids." (PMID 38319971, 2024). "Therefore, the master circadian clock transcription factor heterodimer BMAL1::CLOCK plays a critical role in HCC cell proliferation, irrespective of the robustness of circadian oscillations or other genetic backgrounds, and is relevant to impaired tumor growth in vivo." (PMID 36595671, 2023).